DBR1 (debranching RNA lariats 1)
Description:
Cleaves the 2'-5' phosphodiester linkage at the branch point of excised lariat intron RNA and converts them into linear molecules that can be subsequently degraded, thereby facilitating ribonucleotide turnover. Linked to its role in pre-mRNA processing mechanism, may also participate in retrovirus replication via an RNA lariat intermediate in cDNA synthesis and have an antiviral cell-intrinsic defense function in the brainstem.
Synonyms: XGIP
Tractability: PROTAC: ubiquitination databases record sites on it; its protein half-life has been measured.
Gene: Protein-coding gene on chromosome 3 (138,160,988 to 138,174,949, reverse strand). Ensembl gene ENSG00000138231.
Subcellular location: Nucleus
Subcellular location (Human Protein Atlas): Nucleoplasm
Gene Ontology:
Molecular function: RNA binding; RNA lariat debranching enzyme activity; hydrolase activity; hydrolase activity, acting on ester bonds
Biological process: protein stabilization; RNA fragment catabolic process; RNA splicing, via transesterification reactions; mRNA splicing, via spliceosome; mRNA processing
Cellular component: nucleus
Genetic constraint (gnomAD): Loss-of-function variants: 23 observed, 38.77 expected, observed/expected ratio (o/e) 0.59, 90% interval 0.43 to 0.84. The upper end of that interval is the gene's LOEUF score, 0.84, which puts it in group 3 of 6, group 1 being the genes least tolerant of losing a copy. Missense variants: 515 observed, 591.06 expected, observed/expected ratio (o/e) 0.87, 90% interval 0.81 to 0.94. Synonymous variants: 204 observed, 217.91 expected, observed/expected ratio (o/e) 0.94, 90% interval 0.83 to 1.05.
Homologues: Orthologues: chimpanzee DBR1 (99% identical), macaque DBR1 (98% identical), dog DBR1 (90% identical), pig DBR1 (89% identical), mouse Dbr1 (86% identical), rabbit DBR1 (86% identical), guinea pig DBR1 (86% identical), rat Dbr1 (85% identical), tropical clawed frog dbr1 (60% identical), zebrafish dbr1 (56% identical), Drosophila melanogaster ldbr (44% identical), Caenorhabditis elegans dbr-1 (35% identical).
Diseases named in the same sentence as DBR1 in open-access papers:
DBR1 is named in the same sentence as 9 diseases in open-access papers, as found by Europe PMC text mining. Sharing a sentence is not in itself a finding about the gene and the disease. The quoted sentences say what the papers report.
viral infection (4 papers, 2021 to 2024). "Biallelic mutations in DBR1 were previously found to be associated with aberrant splicing defects, RNA lariat accumulation, and susceptibility to viral infections in the brainstem." (PMID 37800682, 2023). "In addition to the published BP datasets, we revisited our RNA-seq data derived from DBR1-mutated patients with brainstem viral infection." (PMID 36306325, 2022). "Another example, biallelic loss of functions mutations in gene DBR1, (encoding RNA lariat debranching enzyme) which functions in hydrolyzing 2′-to 5′ branches phosphodiester bonds of intron RNA, led to impaired HSV-1 viral infection in the brainstem in a TLR3 independent manner." (PMID 33498715, 2021). "Unlike TLR3–IFN deficiency, which has also been reported in patients with severe viral diseases of tissues other than the brain, such as severe influenza and COVID-19 pneumonia, deficiencies of snoRNA31, RIPK3 and DBR1 have not yet been detected in patients with viral infections of other organs." (PMID 39048830, 2024).
viral encephalitis (3 papers, 2020 to 2024). Encephalitis resulting from viral infection. "In humans, Dbr1 is involved in processes such as class-switch recombination of immunoglobulin genes, and its dysfunction is implicated in viral encephalitis, HIV, ALS, and cancer." (PMID 37507019, 2023). "Brainstem viral encephalitis is rare and was recently identified in several patients carrying mutations in DBR1, which encodes an RNA lariat-debranching enzyme." (PMID 38997413, 2024).
amyotrophic lateral sclerosis (1 paper, 2023). Amyotrophic lateral sclerosis (ALS) is a neurodegenerative disease characterized by progressive muscular paralysis reflecting degeneration of motor neurons in the primary motor cortex, corticospinal tracts, brainstem and spinal cord. "Inhibition of Dbr1 could be protective from amyotrophic lateral sclerosis and other neurodegenerative diseases linked to toxic aggregates of TDP-43." (PMID 37507019, 2023).
cancer (2 papers, 2022 to 2023). A tumor composed of atypical neoplastic, often pleomorphic cells that invade other tissues. "Specifically, several studies focused on human diseases have demonstrated that RNA metabolism controlled by Dbr1 affects cancer development and viral infection." (PMID 36289323, 2022).
infection (1 paper, 2005). The state of being infected such as from the introduction of a foreign agent such as serum, vaccine, antigenic substance or organism. "We found that DBR1 siRNA inhibited the formation of env gene cDNA and complete HIV-1 cDNA twenty-four hours post-infection." (PMID 16232320, 2005). "The accumulation of HIV-1 strong-stop DNA was not affected by DBR1 siRNA expression, while the level of intermediate length and complete HIV-1 cDNA molecules was decreased similarly in the presence of DBR1 siRNA twenty-four hours post-infection." (PMID 16232320, 2005).
neurodegenerative disease (1 paper, 2014). A disorder of the central nervous system characterized by gradual and progressive loss of neural tissue and neurologic function. "Similarly, small-molecule inhibitors of Dbr1 may also find utility in the treatment of neurodegenerative diseases, such as ALS and FTLD, where partial inhibition of Dbr1 allows accumulation of lariat RNAs to sequester toxic forms of the RNA-binding TDP-43 protein." (PMID 25123664, 2014). "Small molecule inhibitors of Dbr1 may therefore be useful in the treatment of TDP-43 mediated ALS and the related neurodegenerative disease frontotemporal lobar degeneration (FTLD)." (PMID 25123664, 2014).
DBR1 also shares sentences with these, for which no sentence is quoted: trichothiodystrophy (2 papers); influenza (1); viral diseases (1).